LRP2 (LDL receptor related protein 2)
Diseases named in the same sentence as LRP2 in open-access papers (continued):
Sharing a sentence is not in itself a finding about the gene and the disease.
Anophthalmia (2 papers, 2016 to 2019). Absence of the globe or eyeball. "The phenotype in humans with a STRA6 mutation includes OFT anomalies, whereas extracardiac anomalies highly resemble the phenotype of the Lrp2 knockout mouse, and humans with an LRP2 mutation with diaphragmatic hernia and anophthalmia." (PMID 26822476, 2016).
chronic kidney disease (2 papers, 2023 to 2024). Impairment of the renal function secondary to chronic kidney damage persisting for three or more months. "Further studies should determine the correlation between LRP2 expression and first intron methylation in other biological systems where LRP2 levels are variable, such as throughout embryonic development or in the settings of acute and chronic kidney diseases." (PMID 36980716, 2023).
clear cell renal cell carcinoma (2 papers, 2017 to 2023). "In a previous unbiased analysis of primary clear cell renal cell carcinomas, low LRP2 was identified as one of 259 genes that predicted poor outcome after surgery." (PMID 36980716, 2023). "Previous studies established LRP2 as an effective target for drug delivery in clear cell renal cell carcinoma." (PMID 36980716, 2023). "Our analysis of patient survival data using TCGA datasets demonstrated a correlation between high levels of LRP2 mRNA expression and increased patient survival in renal clear cell carcinoma." (PMID 29088295, 2017). "Our analysis identified correlations between LRP1 and LRP2 mRNA expression levels and patient survival, but only in bladder urothelial carcinoma and renal clear cell carcinoma, respectively." (PMID 29088295, 2017). "Considerable variability in LRP2 mRNA expression was observed in renal clear cell carcinoma (CV = 0.93)." (PMID 29088295, 2017). "In renal clear cell carcinoma, LRP2 was the most abundantly expressed LRP." (PMID 29088295, 2017).
colorectal cancer (2 papers, 2023 to 2026). A primary or metastatic malignant neoplasm that affects the colon or rectum. "Silencing LRP2 inhibited colorectal cancer (CRC) cell proliferation, migration, and liver metastasis, while enhancing sensitivity to Oxa." (PMID 42215454, 2026).
cystine disease (2 papers, 2020 to 2022). "Expression of DYNC1LI2 (LIC2) preserves LAMP-2A and CMA activity, cell homeostasis, and the localization of LRP2/megalin in cystinotic proximal tubular cells in cystine disease." (PMID 36187470, 2022). "Besides CLCN5 (DD1) and OCRL (Lowe syndrome and Dent disease type 2) genes, they include LRP2 (DB/FOAR), CUBN, AMN (Imerslund–Gräsbeck syndrome), and CTNS (nephropathic cystinosis)." (PMID 31947599, 2020).
deafness (2 papers, 2023 to 2024). An inherited or acquired condition characterized by the complete loss of the ability to hear from one or both ears. "In addition, we identified potentially novel deafness-associated genes Mpzl2 in IMCs and Tbx1 in MCs along with the known deafness-associated genes in IMCs (Kcnj10, Met, Mitf, Gjb6, Ednrb, and Gjb2) and in MCs (Kcnq1, Esrrb, Kcne1, Lrp2, Slc22a4, and Hgf)." (PMID 37322474, 2023). "Another notable gene is LRP2 overlapped between R. pusillus and R. affinis hainanus, which was identified as a deafness gene as well as a candidate echolocation gene associated with the origin of laryngeal echolocation in bats." (PMID 38672325, 2024).
Hyperglycemia (2 papers, 2014 to 2025). An increased concentration of glucose in the blood. "LRP2, which is involved in vitamin uptake, mapped to a chromosomal region (GLUCO15_H on chromosome 2) associated with hyperglycemia." (PMID 24879315, 2014). "Interestingly, Lrp2 is downregulated both by hyperglycemia and LPS, conditions associated with urinary protein loss." (PMID 40579057, 2025).
hypovitaminosis (2 papers, 2015 to 2021). "In the Lrp2-deficient adult mice the brain and eye defects are associated with low molecular weight proteinuria and vitamin deficiency." (PMID 26107939, 2015). "Severe hypovitaminosis D was reported in LRP2 knockout mice, which suggests an important role for LRP2." (PMID 34168679, 2021).
invasive breast carcinoma (2 papers, 2023 to 2025). A carcinoma that infiltrates the breast parenchyma. "It would be natural for such studies to focus on immunohistochemical detection of LRP2, which we previously demonstrated to be useful for the analysis of melanoma tumors and, in the present study, for the analysis of invasive breast carcinomas." (PMID 36980716, 2023). "To confirm protein expression of LRP2 in a cancer of epithelial origin, we performed immunohistochemical analysis of sections of 12 formalin-fixed paraffin-embedded luminal A invasive breast carcinomas." (PMID 36980716, 2023). "Additionally, we confirmed LRP2 protein expression in healthy breast epithelial cells and malignant cells of 12 different invasive breast carcinomas." (PMID 36980716, 2023). "This is consistent with our finding that low LRP2 predicts poor prognosis in the METABRIC cohort and supports that further studies should be conducted in order to evaluate LRP2 as biomarker in invasive breast carcinomas." (PMID 36980716, 2023).
neuroblastoma (2 papers, 2019 to 2021). Neuroblastoma (NB) is the most common solid, extracranial childhood tumor. "Another study, based on human neuroblastoma SH-SY5Y cells, reveals that miR-146a inhibits Lrp2 protein expression and reduces subsequent Akt activation as well as pro-apoptotic caspases-3 induction, which ultimately elevates cell apoptosis in AD." (PMID 33729395, 2021).
ovarian carcinoma (2 papers, 2021 to 2023). A malignant neoplasm originating from the surface ovarian epithelium. "All these studies support our conclusion from this study that NTRK3 and LRP2 might be prognosis biomarkers for Chinese ovarian cancer patients." (PMID 33432021, 2021). "The expression of CYBRD1, LRP2, TFRC, SLC22A17, HEPH, SLC39A14, and PCBP2 involved in iron import was associated with poor OS of ovarian cancer, whereas the expression of LCN2, CP, SLC46A1, STEAP3, and LTF in this process was associated with improved OS in ovarian cancer." (PMID 38186569, 2023). "Conversely, 8 genes showed increased expression in ovarian cancer tissues, including LCN2, CP, TFR2, LRP2, MELTF, LTF, SLC11A2, and STEAP3." (PMID 38186569, 2023). "Together, we deduced that MED12, LRP2, PIK3R2, CCNE1, and LRP1B might be potential biomarkers for immunotherapy of ovarian cancer." (PMID 33432021, 2021).
Retinal dystrophy (2 papers, 2022 to 2025). Retinal dystrophy is an abnormality of the retina associated with a hereditary process. "Congenital high myopia with enlarged eye globes and retinal dystrophy are the main ocular phenotypes of the Donnai–Barrow syndrome caused by LRP2 mutations." (PMID 35833708, 2022).
type 2 diabetes (2 papers, 2021 to 2025). "Our finding that Dapa preserves Lrp2 is concordant with the clinical effects of SGLT2i, reducing renal protein loss in patients with type 2 diabetes." (PMID 40579057, 2025).
AIDS (1 paper, 2019). A syndrome resulting from the acquired deficiency of cellular immunity caused by the human immunodeficiency virus (HIV). "All four were detected in patients with AIDs other than MS; it could therefore be the case that variants of LRP2 are associated with AIDs in general, rather than MS specifically." (PMID 30900415, 2019).
anencephaly (1 paper, 2024). A rare neural tube defect during pregnancy, resulting in the absence of a large portion of the brain and skull in the fetus. "Variants of Lrp2 in humans with NTDs, resulting in anencephaly and myelomeningocele, and found that folic acid supplementation alone did not help." (PMID 38771546, 2024).
anorexia nervosa (1 paper, 2014). A disorder most often seen in adolescent females characterized by a refusal to maintain a minimally normal body weight, an intense fear of gaining weight, a disturbance in body image, and, in postmenarcheal females, the development of amenorrhea. "Curiously, a higher significance level for a single nucleotide polymorphism (SNP) within the LRP2 gene (p = 8.68 × 10−6) was found in a GWAS of patients with anorexia nervosa." (PMID 25158045, 2014).
atherosclerosis (1 paper, 2024). A disease characterized by the build-up of fatty material and calcium deposition in the arterial wall resulting in partial or complete occlusion of the arterial lumen. "Pharmacological inhibition of megalin (also known as low-density lipoprotein receptor-related protein 2: LRP2) attenuates atherosclerosis in hypercholesterolemic mice." (PMID 38798535, 2024). "Since our previous study has confirmed that control ASO showed comparable results as PBS (the solvent for ASOs) on blood pressure and atherosclerosis, PBS injection was used as the negative control (vehicle) of Lrp2 ASO." (PMID 38798535, 2024).
autoimmune uveitis (1 paper, 2019). An autoimmune form of uveitis (disease). "LRP2 variant rs34355135 was detected in two individuals with RRMS, one of whom also had autoimmune uveitis, from a type‐B family." (PMID 30900415, 2019). "LRP2 variant rs34564141 was observed in two patients with RRMS associated with another AID (ulcerous colitis and Guillain‐Barré syndrome), one individual with autoimmune uveitis, and one unaffected individual from a type‐B family." (PMID 30900415, 2019).
Autoimmunity (1 paper, 2020). The occurrence of an immune reaction against the organism's own cells or tissues. "We now put these findings in context within the wider frame of autoimmunity against megalin/LRP2 and related antigens such as Fx1A and CD69." (PMID 32701075, 2020).
bladder urothelial carcinoma (1 paper, 2022). "The results showed that in bladder urothelial carcinoma, rectal adenocarcinoma and endometrial carcinoma, patients with LRP2 mutations had significantly higher TMB than those without LRP2 mutations." (PMID 35834061, 2022).
cervical cancer (1 paper, 2024). A primary or metastatic malignant neoplasm involving the cervix. "The results revealed that, compared with the control group, knockdown of BOC and LRP2 inhibited the proliferation of cervical cancer cells." (PMID 39346724, 2024). "Additionally, we found that knockdown of BOC or LRP2 inhibits the proliferation of cervical cancer cells." (PMID 39346724, 2024). "However, the potential roles of BOC and LRP2 in cervical cancer remain largely unexplored." (PMID 39346724, 2024). "Subsequently, the impact of LRP2 and BOC on the proliferation of cervical cancer cells was assessed using CCK-8 analysis." (PMID 39346724, 2024). "Initially, our findings suggest that CLPTM1L may influence cervical cancer cell proliferation through downstream candidate genes BOC and LRP2, while also playing a crucial role in regulating cisplatin-induced apoptosis via DAP1." (PMID 39346724, 2024).
Chorioretinal atrophy (1 paper, 2015). Atrophy (wasting) of the choroid and retinal layers of the fundus. "In addition to the enlarged vitreal chamber the modifications of the Lrp2-deficient posterior segment include retinal thinning and chorioretinal atrophy." (PMID 26107939, 2015).
colorectal adenocarcinoma (1 paper, 2022). The most common type of colorectal carcinoma. "In this study, we found that LRP2 mutations were associated with high levels of TMB and MSI in various tumor types, especially for endometrial cancer, colorectal adenocarcinoma and esophagogastric adenocarcinoma." (PMID 35834061, 2022). "The results exhibited that in colorectal adenocarcinoma, endometrial carcinoma and esophagogastric adenocarcinoma, patients with LRP2 mutations had higher MSIsensor score than those without LRP2 mutations." (PMID 35834061, 2022).
Crohn disease (1 paper, 2025). A gastrointestinal disorder characterized by chronic inflammation involving all layers of the intestinal wall, noncaseating granulomas affecting the intestinal wall and regional lymph nodes, and transmural fibrosis. "Mutations in the LRP2 gene are risk factors for Parkinson’s disease, Crohn’s disease, leprosy, and some cancers whose pathogenesis is associated with macro-autophagy/autophagy." (PMID 40529366, 2025).
cyst (1 paper, 2021). A sac-like closed membranous structure that may be empty or contain fluid or amorphous material. "We studied the cell origin of cyst epithelial cells by conducting differential gene expression analysis and established genetic markers (LRP2, SLC12A1, CDH16, and KRT17) 21, 22 of renal tubules and CD in the epithelial cell populations, respectively." (PMID 34815804, 2021). "We validated the clustering outcomes by using specific antibodies for different nephron segments, including LRP2, SLC12A1, CDH16, KRT17 and two classical markers CD10 and AQP2(the marker of PT and CD, respectively) for IHC staining of cyst epithelial cells." (PMID 34815804, 2021).
cystinuria (1 paper, 2020). Cystinuria is a renal tubular amino acid transport disorder characterized by recurrent formation of kidneys cystine stones. "In fact, we identified in two patients (AMS and BDA) biallelic likely pathogenic variants in two genes (SLC3A1, LRP2) whose mutations are known to cause cystinuria and DB/FOAR." (PMID 31947599, 2020). "In two adults patients (AMS and BDA), we detected biallelic likely pathogenic variants in SLC3A1 and LRP2 genes whose mutations are responsible for the recessive diseases Cystinuria (MIM#220100) and Donnai–Barrow/Facio-oculo-acoustico-renal syndrome (DB/FOAR, MIM#222448), respectively." (PMID 31947599, 2020).
endometrial carcinoma (1 paper, 2022). A malignant tumor arising from the epithelium that lines the cavity of the uterine body. "In the endometrial cancer (EC) cohort, we found that patients with LRP2 mutations belonged to the POLE and MSI-H type and had a better prognosis." (PMID 35834061, 2022).
esophageal carcinoma (1 paper, 2015). A primary or metastatic malignant neoplasm involving the esophagus. "It promotes cancer cell metastasis and invasion in esophageal carcinoma, which transfers iron by snatching siderophores through its receptor, LRP2." (PMID 26131602, 2015).
even-plus syndrome (1 paper, 2025). "For example, MAN2C1 is associated with congenital disorder of deglycosylation 2 (MIM #619775), GPHN with molybdenum cofactor deficiency C (MIM #615501), LRP2 with Donnai–Barrow syndrome (MIM #222448), and HSPA9 with Even-plus syndrome (MIM #616854)." (PMID 40282865, 2025).
glioblastoma multiforme (1 paper, 2023). "Moderate levels of LRP2 were detected in low-grade glioma (LGG) and glioblastoma multiforme (GBM), although there have only been a few reports of LRP2 expression in the brain and spinal cord." (PMID 36980716, 2023).
granulosa cell tumor (1 paper, 2021). A slow-growing, malignant tumor, characterize by the presence of granulosa-like cells and Call-Exner bodies, that is almost always found in the ovary. "Although predicted deleterious variants in PIK3C2G, BMP5, and LRP2 were found, we could not identify an overlapping genetic variant or affected locus that may explain a genetic predisposition for granulosa cell tumors." (PMID 34069790, 2021).
head and neck cancer (1 paper, 2023). A primary or metastatic malignant neoplasm affecting the head and neck. "Notably, the KMT2C-PTDSS1 SL pair emerges prominently in the bile duct, brain, breast, gastric, lung, and head and neck cancers, while the LRP2-PTDSS1 SL pair is prevalent in breast, ovarian, lung, and head and neck cancers." (PMID 37737478, 2023).
hepatocellular carcinoma (1 paper, 2026). A malignant tumor that arises from hepatocytes.
hypopituitarism (1 paper, 2014). A condition of diminution or cessation of secretion of one or more hormones from the anterior pituitary gland. "These support the hypothesis that LRP2 sequence variants might lead to abnormalities in pituitary development and hypopituitarism." (PMID 25158045, 2014).
lymph node metastasis (1 paper, 2022). "This study constructed a prognostic model of genes related to lymph node metastasis in COAD and found that PMCH, CD1B, NAT1, NKAIN4, and LRP2 have prognostic, predictive values." (PMID 36727052, 2022). "The high expression of NKAIN4 and LRP2 is related to the poor prognosis of COAD patients and has a co-expression relationship with the immune infiltrating cells related to lymph node metastasis." (PMID 36727052, 2022). "Thus, we infer that the relevant mechanism between LRP2 and COAD lymph node metastasis may not be related to reducing vitamin D but to other effects of LRP2, such as the reuptake of many ligands and signal transduction." (PMID 36727052, 2022).
macular holes (1 paper, 2025). A hole in the macula of the retina. "LRP2 levels were evaluated in vitreous samples of patients with HM and PS who underwent pars plana vitrectomy for myopic tractional maculopathy, macular hole, or epiretinal membrane and compared to vitreous from emmetropic patients operated for epiretinal membrane or for intraocular lens luxation." (PMID 40553567, 2025).
malaria (1 paper, 2017). Malaria is a serious and sometimes fatal disease caused by a parasite that commonly infects a certain type of mosquito which feeds on humans. "While the LRP connection to malaria entry is an interesting parallel, the over-expression of LRP2 may be attributable to other processes in the host cell." (PMID 28462779, 2017).
ocular melanoma (1 paper, 2025). A melanoma that arises from the structures of the eye or ocular adnexa. "Our data diverge from this cutaneous pattern: in ocular melanoma, we observed consistent downregulation rather than acquisition of LRP2, indicating tissue-specific differences in LRP2′s role along the melanocytic lineage." (PMID 41374987, 2025).
ocular tumors (1 paper, 2025). "Our results are consistent with this pattern, as ocular tumors also showed LRP2 loss in association with dedifferentiation." (PMID 41374987, 2025). "Taken together, these findings indicate that LRP2 behaves in a tumor-suppressor-like, differentiation-linked manner in ocular tumors (consistent with our downregulation)." (PMID 41374987, 2025). "Yet their distribution and function in ocular tumors remain insufficiently defined, despite LRP2-dependent signaling control and critical endocytic homeostasis in the eye." (PMID 41374987, 2025). "Our protein-level observation of LRP2 downregulation in ocular tumors was directly corroborated at the mRNA level in GSE208143 (RB vs. control retina), where LRP2 transcripts were significantly reduced." (PMID 41374987, 2025). "Integration with public datasets highlights CAV1 and GIPC1 as adverse survival correlates in UM and positions LRP2/CUBN/DAB2IP dysregulation as features of ocular tumor biology, nominating candidate biomarkers and mechanistic targets." (PMID 41374987, 2025).
Oral leukoplakia (1 paper, 2021). A thickened white patch on the oral mucosa that cannot be rubbed off. "This study aimed to assess the relationship and possible interactions between metallothioneins (MTs) and megalin (LRP-2) in different grades of oral squamous cell carcinoma (OSCC) and premalignant lesions of the oral mucosa (oral leukoplakia and oral lichen planus)." (PMID 34572758, 2021).
osteomalacia (1 paper, 2023). Disorder caused by an interruption of the mineralization of organic bone matrix leading to bone softening, bone pain, and weakness. "This hypothesis was based on a study of knockout mice for Lrp2 (encoding for megalin) with very bad osteomalacia and poor survival, revealing the important function of the DBP binding capacity in the kidney." (PMID 37505607, 2023).